SNAPC5 (small nuclear RNA activating complex polypeptide 5)
Description:
Part of the SNAPc complex required for the transcription of both RNA polymerase II and III small-nuclear RNA genes. Binds to the proximal sequence element (PSE), a non-TATA-box basal promoter element common to these 2 types of genes. Recruits TBP and BRF2 to the U6 snRNA TATA box.
Synonyms: SNAP19
Tractability: PROTAC: ubiquitination databases record sites on it.
Gene: Protein-coding gene on chromosome 15 (66,490,135 to 66,497,780, reverse strand). Ensembl gene ENSG00000174446.
Subcellular location: Nucleus
Subcellular location (Human Protein Atlas): Nucleoplasm
Pathways (Reactome):
Gene expression (Transcription): RNA Polymerase III Abortive And Retractive Initiation; RNA Polymerase III Transcription Initiation From Type 3 Promoter; RNA polymerase II transcribes snRNA genes
Gene Ontology:
Molecular function: protein binding; RNA polymerase II general transcription initiation factor activity; RNA polymerase III general transcription initiation factor activity
Biological process: snRNA transcription by RNA polymerase II; snRNA transcription by RNA polymerase III; transcription by RNA polymerase II; transcription initiation at RNA polymerase III promoter
Cellular component: nucleoplasm; snRNA-activating protein complex; nucleus
Genetic constraint (gnomAD): Loss-of-function variants: 5 observed, 4.95 expected, observed/expected ratio (o/e) 1.01, 90% interval 0.52 to 1.81. That is too few expected variants to judge how well the gene tolerates losing a copy. Missense variants: 76 observed, 70.01 expected, observed/expected ratio (o/e) 1.09, 90% interval 0.9 to 1.31. Synonymous variants: 38 observed, 33.11 expected, observed/expected ratio (o/e) 1.15, 90% interval 0.88 to 1.5.
Homologues: Orthologues: chimpanzee SNAPC5 (100% identical), macaque SNAPC5 (100% identical), dog SNAPC5 (90% identical), rabbit SNAPC5 (87% identical), pig SNAPC5 (86% identical), mouse Snapc5 (78% identical), rat Snapc5 (77% identical), zebrafish snapc5 (51% identical).
Diseases named in the same sentence as SNAPC5 in open-access papers:
SNAPC5 is named in the same sentence as 3 diseases in open-access papers, as found by Europe PMC text mining. Sharing a sentence is not in itself a finding about the gene and the disease. The quoted sentences say what the papers report.
breast invasive carcinoma (1 paper, 2019). "The interactive network shows that SNAPC5, PCBP2 and GNA13 are connected to other frequently altered genes from the TCGA breast invasive carcinoma dataset, which are also selected by other competing methods." (PMID 31534156, 2019).
cancer (2 papers, 2022 to 2023). A tumor composed of atypical neoplastic, often pleomorphic cells that invade other tissues. "Mitochondrial RNA polymerase (POLRMT) is often reported as a target protein for the treatment of malignant tumours, however snRNA-activating protein complex 5 (SNAPC5), also named SNAP19, has rarely been reported in tumours." (PMID 37441804, 2023). "Then, a CDM signature with five cancer-dependent genes (MMS19, NOP14, POLRMT, SNAPC5 and TIGD1) and a prognostic nomogram were constructed, and they demonstrated robust predictive performance and a close relationship with clinical characteristics in different CC datasets." (PMID 37441804, 2023). "Despite the lack of documentation of SNAPC5’s involvement in cancers, the results of this research suggest that further investigation will be needed." (PMID 35957812, 2022).
SNAPC5 also shares sentences with these, for which no sentence is quoted: tumours (1 paper).